CD81 (CD81 molecule)
Diseases named in the same sentence as CD81 in open-access papers (continued):
Sharing a sentence is not in itself a finding about the gene and the disease.
colitis (2 papers, 2020 to 2024). Inflammation of the colon. "Treatment with anti-CD81 antibodies improved colitis scores, reduced colon shortening, decreased loss of body weight, and resulted in fewer pathological changes of the colon in colitic mice." (PMID 32332834, 2020). "Single-cell transcriptomic profiling of chronic dextran sulfate sodium salt murine colitis model revealed that CD81+Pi16– fibroblasts exhibited transcriptomic and functional similarities to human FAP+ fibroblasts." (PMID 39024569, 2024). "IL-17+ T cells from mice with established TNBS-induced colitis were rich in CD81+ T cells at 3.7-fold (11.9% versus 3.2%) and 19-fold (3.8% versus 0.2%) compared with CD81− T cells with or without SEB stimulation, respectively." (PMID 32332834, 2020). "The effect of an anti-CD81 antibody on acute intestinal inflammation was examined in mice with acute colitis." (PMID 32332834, 2020). "The anti-CD81 antibody inhibited the migration of splenocytes from mice with TNBS-induced colitis, which was induced by SDF-1, one of the ligands for chemokine receptor CXCR4 and a chemokine involved in the pathogenesis of IBD 1,8." (PMID 32332834, 2020). "Histological analysis of DSS-induced colitis mice showed features of colitis, such as depletion of mucus and cell infiltration in the mucosa, and the anti-CD81 antibody treatment improved these pathological changes." (PMID 32332834, 2020). "IFNγ+ T cells in established TNBS-colitis mice were rich in CD81+ T cells at 3.7-fold (12.8% versus 3.5%) or 4.9-fold (6.4% versus 1.3%) compared with CD81− T cells with or without SEB stimulation, respectively." (PMID 32332834, 2020). "We showed that two different anti-mouse CD81 antibody clones, 2F7 and Eat2, were both effective against colitis, although Eat2 was more effective than 2F7." (PMID 32332834, 2020). "Mice with established TNBS-induced colitis treated with the anti-CD81 antibody had increased body weights compared with vehicle-treated mice, and the difference in the body weight change over 7 days was statistically significant." (PMID 32332834, 2020). "Next, we investigated the mechanism of the effect of the anti-mouse CD81 antibody on TNBS-induced colitis, focusing on T cell functions using the clone Eat2." (PMID 32332834, 2020). "The length of the colons of mice with TNBS-induced colitis was shortened compared with that of untreated mice, and treatment with the anti-CD81 antibody and SSZ significantly improved the colon length." (PMID 32332834, 2020). "Mice with established TNBS-induced colitis were administered the anti-mouse CD81 antibody (clone 2F7) and histopathological changes were examined for 7 days." (PMID 32332834, 2020). "Therapeutic effects of anti-CD81 antibodies on colitic symptoms and inflammation were evaluated in mice with colitis, including long-term effects of the antibodies." (PMID 32332834, 2020). "Although there were eight mice with established colitis per group, one to three mice in each group died despite the reduction of the colitis score by anti-CD81 antibody and SSZ treatments." (PMID 32332834, 2020). "We examined the mechanism underlying the therapeutic effect of the anti-CD81 antibody and found that CD4+ T cells were decreased in colons of mice with colitis treated with the anti-CD81 antibody." (PMID 32332834, 2020). "CXCR4+ T cells in mice with established TNBS-induced colitis were enriched among CD81+ T cells by 2.6- or 3.9-fold versus CD81− T cells with or without SEB stimulation, respectively." (PMID 32332834, 2020). "Treatment with the anti-CD81 antibody at 0.2 mg/mouse significantly reduced the colitis score not only on days 4 and 5, but also from day 18 to 20 compared with the vehicle group." (PMID 32332834, 2020). "The anti-CD81 antibody ameliorated the colitis score and improved colon lengths in mice with DSS-induced colitis." (PMID 32332834, 2020).
colitis (continued). "TNBS-induced colitis mice had inflamed and thickened colons, and anti-CD81 antibody treatment improved these pathological changes." (PMID 32332834, 2020). "The length of the colons in mice with DSS-induced colitis was shortened compared with those in untreated mice, and treatment with the anti-CD81 antibody at 0.2 mg/mouse significantly improved the colon length." (PMID 32332834, 2020). "Moreover, the anti-CD81 antibody improved colitic symptoms and body weight change of mice with a flare-up of TNBS-induced colitis after stopping anti-CD81 antibody treatment." (PMID 32332834, 2020). "Therefore, it was likely that the anti-CD81 antibody reduced migration of effector T cells in mice with colitis and improved colonic inflammation." (PMID 32332834, 2020). "Notably, the colitis score on day 7 was significantly reduced by both the anti-CD81 antibody and SSZ compared with the vehicle group." (PMID 32332834, 2020). "Moreover, the anti-CD81 antibody attenuated the colitis score significantly from day 23 to 28 compared with SSZ." (PMID 32332834, 2020). "Finally, we assessed the therapeutic potential of the anti-CD81 antibody in another colitis model, DSS-induced colitis." (PMID 32332834, 2020). "In addition, mice with DSS-induced colitis and treated with the anti-CD81 antibody at 0.2 mg/mouse had improved body weights on days 18 and 19 compared with vehicle-treated mice." (PMID 32332834, 2020). "This function of CD81 may be involved in the reset of inflammatory lymphocytes in colitis and contribute to the long-lasting effect of anti-CD81 antibodies." (PMID 32332834, 2020). "Moreover, overall, CD81+ cells in the colons of mice with TNBS-induced colitis were increased compared with those of untreated mice." (PMID 32332834, 2020). "Although anti-CD81 antibodies had no influence on the proliferation or cytokine release of stimulated lymphocytes from mice with colitis, the anti-CD81 antibody reduced migration of lymphocytes from both colitic mice and that of a mouse T cell line towards SDF-1." (PMID 32332834, 2020). "However, CD69+ T cells from untreated mice with established TNBS-induced colitis were enriched for CD81+ T cells by 2.1–3.2-fold versus CD81− T cells with or without staphylococcal enterotoxin B (SEB) stimulation." (PMID 32332834, 2020). "Two different clones of the anti-mouse CD81 antibody were also effective in mice with colitis." (PMID 32332834, 2020). "However, because this inhibitory effect was not complete, other mechanisms may contribute to the therapeutic effect of the anti-CD81 antibody on murine colitis." (PMID 32332834, 2020). "Thus, CD81 was increased on activated T cells in mice with colitis." (PMID 32332834, 2020). "We examined the contribution of CD81 to the pathology of IBD using anti-mouse CD81 antibodies and 2,4,6-trinitrobenzenesulfonic acid (TNBS)-induced colitis to determine its therapeutic potential for IBD." (PMID 32332834, 2020). "CD81+ T cells among lymphocytes of the Peyer’s patches and mesenteric lymph nodes of mice with TNBS-induced colitis were increased compared with those of untreated mice." (PMID 32332834, 2020). "Therefore, we hypothesised that CD81 regulated TNBS-induced colitis." (PMID 32332834, 2020). "We found increased CD81 expression on T cells in peripheral blood and Peyer’s patches of mice with TNBS-induced colitis." (PMID 32332834, 2020). "Treatment with the anti-CD81 antibody on days 0, 2, and 4 and daily administration of sulfasalazine (SSZ) attenuated the colitis score." (PMID 32332834, 2020). "In addition, as another clone of anti-CD81 antibody, Eat1 was also effective against TNBS-induced colitis." (PMID 32332834, 2020). "We showed that the anti-mouse CD81 antibody improved colitic symptoms, including shortened inflamed colons and reduced body weight, and attenuated histological changes in colons and inflammatory markers in the blood of mice with acute TNBS-induced colitis." (PMID 32332834, 2020).
colitis (continued). "Thus, the anti-CD81 antibody reduced migration of activated T cells, which attenuated intestinal inflammation in the TNBS-induced model of colitis." (PMID 32332834, 2020). "The anti-mouse CD81 antibody also had no influence on the cytokine production of splenocytes from mice with TNBS-induced colitis, which were stimulated with the immobilised anti-mouse CD3ε antibody or SEB." (PMID 32332834, 2020). "Finally, we confirmed the therapeutic potential of the anti-CD81 antibody in another model, DSS induced colitis." (PMID 32332834, 2020). "In addition, another anti-CD81 antibody, Eat1, ameliorated TNBS-induced colitis." (PMID 32332834, 2020). "Because CD81 was degraded by digestive enzymes in the preparation of colonic cells, the action of the anti-mouse CD81 antibody was determined on splenocytes and not colonic cells in mice with TNBS-induced colitis." (PMID 32332834, 2020).
dementia (2 papers, 2024). Loss of intellectual abilities interfering with an individual's social and occupational functions. "Moreover, multiplex analysis of single exosomes from the CSF of Parkinson's disease dementia (PDD) patients via solid-state technology revealed various surface markers, such as CD9, CD63, and CD81." (PMID 39431275, 2024).
experimental autoimmune encephalomyelitis (2 papers, 2020 to 2025). An autoimmune demyelinating disease of the central nervous system that is produced experimentally in animals by the injection of homogenized brain or spinal cord in Freund's adjuvant. "CD16+ monocytes showed downregulation of select transcription factor genes (RXRA, IKZF1, KLF4, IRF4) and CD81, a marker that facilitates monocytes homing to the CNS in experimental autoimmune encephalomyelitis (EAE)." (PMID 40067358, 2025).
hepatoblastoma (2 papers, 2019 to 2021). Hepatoblastoma (HB) is a malignant hepatic tumor and is the most common pediatric liver cancer. "The other hepatoblastoma tumor showed positivity for CD10, CD9, CD81, CD105 in the absence of GD2, EpCAM, CD99, numyogenin, and CD90." (PMID 34638431, 2021).
Hypertension (2 papers, 2023 to 2024). The presence of chronic increased pressure in the systemic arterial system. "Thus, the upregulation of renal CD81 on NKCC2 and NCC may contribute to the sustained hypertension observed in LPS-PE model." (PMID 36961378, 2023).
psoriasis (2 papers, 2022 to 2024). An autoimmune condition characterized by red, well-delineated plaques with silvery scales that are usually on the extensor surfaces and scalp. "We identified GZMB, GNAS, GBP5, FOXP3, LSP1 and CD81 as characteristic genes of psoriasis-associated CD8+ T cells, among which, Granzyme B (GzmB), a serine protease, is produced by natural killer (NK) cells and CD8+ T cells, and is an vital mediator of skin injury, inflammation and repair." (PMID 38915827, 2024).
Rb (2 papers, 2022 to 2024). "Due to sample scarcity, we focused on Case 79 AH to further explore the association of known EV tetraspanins (CD9, CD63, and CD81) with the CD133 signal in RB samples." (PMID 39519212, 2024). "Immune-related genes such as CD86, CD19, and CD36 were significantly upregulated in advanced Rb while displaying a low degree of expression of CD81 and CD163." (PMID 35626705, 2022). "In comparison to the GLC patients, the analysis of EVs in the AH of the 5 RB samples exhibited a much larger co-dominance of CD63/CD81 positivity, consistent with past research on RB EVs." (PMID 39519212, 2024). "The mean CD81 enrichment ratio for the five RB samples was 1.5 (SD = 0.26) vs. 0.3 (SD = 0.24) for the two GLC samples (p = 0.095)." (PMID 39519212, 2024).
Zika virus infection (2 papers, 2021 to 2024). "We also found that monocyte ZIKV infection induced tetraspanin CD63 internalization and translocation of tetraspanin CD81 and ESCRT-associated proteins TSG101 and Alix to the plasma membrane." (PMID 38247836, 2024). "Altogether, these results suggest that Zika virus infection and transmissive capabilities are compromised due to overexpression of CD9, CD63, and CD81." (PMID 34190582, 2021).
allergic reactions (1 paper, 2014). "In T cells, several tetraspanin proteins, including CD9, CD81 and CD82 are reported to associate with CD4 or CD8 and enhance T cell effector functions, while CD81 negatively modulates FcεRI-mediated degranulation in mast cells and suppress IgE-dependent allergic reactions." (PMID 24832104, 2014).
amyotrophic lateral sclerosis (1 paper, 2022). Amyotrophic lateral sclerosis (ALS) is a neurodegenerative disease characterized by progressive muscular paralysis reflecting degeneration of motor neurons in the primary motor cortex, corticospinal tracts, brainstem and spinal cord. "MMP9 and CD81 gene products are involved in cell motility and extracellular matrix dynamics, MMP9 expression changes in PD, and amyotrophic lateral sclerosis." (PMID 35085348, 2022).
anaplastic astrocytoma (1 paper, 2020). "Similar findings were obtained for the FASN+/CD63+ EV population in anaplastic astrocytoma patients (mean 2.9 × 105/mL AA vs 5.8 × 104/mL HD, P = 0.005) as well as for the FASN+/CD81+ EV population (mean 5.2 × 105/mL AA vs 2.3 × 105/mL HD, P = 0.03)." (PMID 32178271, 2020).
antibody deficiency syndrome (1 paper, 2024). "It has been shown that mutations in CD81 resulted in disruption of CD19 complex formations on B cell leading to antibody deficiency syndrome in humans." (PMID 39400515, 2024).
Anxiety (1 paper, 2024). Intense feelings of nervousness, tension, or panic often arise in response to interpersonal stresses. "However, previous publications linked CD81 expression in the brain to anxiety regulation and ethanol sedation." (PMID 39931524, 2024).
Arthritis (1 paper, 2024). Inflammation of a joint. "Previously, CD9 or CD81 deficiency induced protective effects on articular cartilage in rodent models of arthritis, but earlier studies on the connections of EV tetraspanins and cartilage degradation remain scarce." (PMID 38254142, 2024). "On the other hand, anti-CD81 vectors administered into the ankle joints of rats with collagen-induced arthritis suppressed joint destruction." (PMID 38254142, 2024). "The roles of tetraspanins in arthritis remain unresolved, but their profiles have been studied in the plasma EVs of RA patients, who had higher proportions of single-positive CD81 and CD9 sEVs but lower levels of double-positive CD81/CD9 sEVs than healthy controls." (PMID 38254142, 2024).
Ascites (1 paper, 2025). Accumulation of fluid in the peritoneal cavity (between the layers of the peritoneum that lines the abdomen). "Compared to the sh‐CD81 group, PCS administration increased the body weight and volume of ascites in the sh‐CD81 + PCS group." (PMID 40604335, 2025).
atopic dermatitis (1 paper, 2023). "The expression of the tetraspanins such as CD9, CD37, CD53, CD63, CD81, and CD82 on FcεRIpos skin dendritic cells (DCs) from atopic dermatitis patients is significantly higher when compared to skin DCs of not allergic healthy individuals." (PMID 36672710, 2023).
atrial fibrillation (1 paper, 2025). A disorder characterized by an electrocardiographic finding of a supraventricular arrhythmia characterized by the replacement of consistent P waves by rapid oscillations or fibrillatory waves that vary in size, shape and timing and are accompanied by an irregular ventricular response. "In the atrial fibrillation dataset, LDHB, PFKFB2, CKAP4, CXCR4, DPEP2, and RORA genes showed an upregulation trend, while only the CD81 gene was downregulated in the disease group." (PMID 41359645, 2025).
autoimmune disease (1 paper, 2023). A disorder resulting from loss of function or tissue destruction of an organ or multiple organs, arising from humoral or cellular immune responses of the individual to their own tissue constituents. "However, the recently reported structures of the IgM- and IgG-BCRs, and the BCR co-receptors CD19, CD81 and CD22 will help guide the rational design of antibodies, nanobodies, and miniproteins for the treatment of B cell malignancies and autoimmune diseases." (PMID 37296844, 2023).
B-cell CLL (1 paper, 2022). "The under-expression of CD81, CD79b, and positive CD43 and ROR1 expression, noted in the DURAClone CLB panel specifically assists in distinguishing B-cell CLL from mantle cell lymphoma and other CD5 negative B-cell LPDs." (PMID 36483322, 2022).
cataract (1 paper, 2018). Partial or complete opacity of the crystalline lens of one or both eyes that decreases visual acuity and eventually results in blindness. "Here, we found that CD9/CD81 double knockout (DKO) mice with a COPD-like phenotype progressively developed a syndrome resembling human aging, including cataracts, hair loss, and atrophy of various organs, including thymus, muscle, and testis, resulting in shorter survival than wild-type (WT) mice." (PMID 29572511, 2018).
cholangiocarcinoma (1 paper, 2015). A carcinoma that arises from the intrahepatic biliary tree (intrahepatic cholangiocarcinoma) or from the junction, or adjacent to the junction, of the right and left hepatic ducts (hilar cholangiocarcinoma). "To investigate HCV entry factor expression in vivo we stained cholangiocarcinoma liver tissue from two donors with antibodies specific for CD81, SR-BI, claudin-1, occludin and epithelial marker CK19." (PMID 25701818, 2015). "To investigate the receptor dependency of HCVpp infection of the permissive cholangiocarcinoma lines, we assessed the ability of anti-CD81 and anti-SR-BI antibodies to inhibit HCVpp (strain H77) infection." (PMID 25701818, 2015). "Cholangiocarcinoma from both donors expressed all four HCV entry factors, albeit with low CD81 expression, whereas biliary epithelia from the normal non-tumour margin lacked SR-BI expression." (PMID 25701818, 2015).
chondrosarcoma (1 paper, 2021). A malignant cartilaginous matrix-producing mesenchymal neoplasm arising from the bone and soft tissue. "In turn, tumor cells from the only chondrosarcoma (CDS) analyzed were also positive for GD2 and CD9, in addition to CD81 and CD90, and they lacked CD10, CD58, nuMyoD1, numyogenin, CD57, and CD99 expression." (PMID 34638431, 2021).
clear cell sarcoma (1 paper, 2021). A rare malignant neoplasm with melanocytic differentiation characterized by the presence of polygonal or spindle shaped clear cells. "Other less prevalent malignant kidney tumors included a renal cell carcinoma (RC), which showed a CD271+ CD81+ EpCAM+ CD71+ CD117+ phenotype in the absence of CD9, CD10, CD58, CD90, CD105, and GD2, and a clear cell sarcoma, which expressed CD271+ and GD2+ without EpCAM." (PMID 34638431, 2021).
cyst (1 paper, 2023). A sac-like closed membranous structure that may be empty or contain fluid or amorphous material. "We show that cyst fluid is a rich source of EVs that are positive and negative for the EV markers CD63 and CD81, respectively." (PMID 37963969, 2023).
disc degeneration (1 paper, 2023). "Cluster 5 exhibited the most distinction and is marked by expression of alarmins and the surface antigens Cd81 and Cd151; thus, these surface markers could be used to specifically isolate and define the roles of this macrophage subset to disc degeneration." (PMID 38274272, 2023).
embryonal carcinoma (1 paper, 2019). A non-seminomatous malignant germ cell tumor characterized by the presence of large germ cells with abundant cytoplasm resembling epithelial cells, geographic necrosis, high mitotic activity, and pseudoglandular and pseudopapillary structures formation. "The differences in staining intensity (according to the immunoreactivity staining score (IRS)) of CD81 observed between seminomas and embryonal carcinomas were marked and showed a statistical significance." (PMID 31565104, 2019). "Interestingly, in our study, we could demonstrate that CD81 showed marked differences in its expression when comparing seminoma (high expression) and embryonal carcinoma tissue samples (low expression)." (PMID 31565104, 2019). "In contrast, no or only a weak staining of CD81 was seen in embryonal carcinoma cells (arrow)." (PMID 31565104, 2019).